AGER (advanced glycosylation end-product specific receptor)
Diseases named in the same sentence as AGER in open-access papers (continued):
Sharing a sentence is not in itself a finding about the gene and the disease.
tumor (continued). "Furthermore, multiple receptors interacting with different S100 proteins or S100A8/A9 heterodimers are expressed by both tumor cells and TAMs (SCARA/B, CD36), preferentially by TAMs (AGER, MSR1, TLR4) or by tumor cells (ERBB2), pointing to extensive functional interactions between both cell types." (PMID 27215396, 2016). "The knockdown of advanced glycosylation end product-specific receptor (AGER), the receptor of S100A9, eradicates the NF-κB-mediated pro-tumorigenic effects of S100A9, suggesting that S100A9 controls the crosstalk between tumor cells and TAMs and could be a potential target for treating HCC patients." (PMID 38397187, 2024). "The IHC showed that AGER and PECAM1 have high intensity and strong staining in all normal lung samples (3/3 subjects), whereas in LUAD tumor tissues, these proteins were absent (0/5–6 showed any positive staining)." (PMID 40563443, 2025). "The biomarker signature identified in this study, more specifically AGER and MGP, has unique methylation patterns in tumor versus normal tissues." (PMID 40563443, 2025). "Interestingly, we showed increased AGER expression in triple-negative IBC compared to non-IBC samples, which might contribute to the worse prognosis frequently described in these tumor types." (PMID 40647480, 2025).
cancer (76 papers, 2009 to 2025). A tumor composed of atypical neoplastic, often pleomorphic cells that invade other tissues. "The single nucleotide polymorphism (SNP) of AGER, rs1800624 (-374T/A), reduces the risk of cancer and Crohn’s disease, and protects against the development of CVD in both diabetic and non-diabetic patients." (PMID 34204735, 2021). "Other AGER variants, such as rs2070600 (G82S), have been shown to favor diabetic complications and cancer." (PMID 34204735, 2021). "In vitro studies demonstrated that co-culturing AGER-depleted human LC cells (H358) with lung fibroblasts (WI38) significantly enhanced cancer cell proliferation." (PMID 40853920, 2025). "Ferroptotic cancer cells release HMGB1 to promote the inflammatory responses of macrophages through binding to AGER." (PMID 34796174, 2021). "HMGB1 released by ferroptotic cancer cells is a prototypical DAMP involved in the immunogenicity of cancer cells, and it triggers an inflammatory response in macrophages through binding to advanced glycosylation end-product-specific receptor (AGER/RAGE)." (PMID 34796174, 2021). "Our results showed that up-regulation of AGER in SiHa and Caski cells significantly promoted cancer cell growth, conversely, down-regulation of AGER expression in SiHa cells inhibited cell proliferation." (PMID 29298878, 2018). "The receptor for advanced glycation end products (AGER) is an oncogenic transmembranous receptor up-regulated in various human cancers." (PMID 29298878, 2018). "AGER expression in pan-cancer was obtained by using the UALCAN databases." (PMID 37497166, 2023). "The results showed that TPX2 and BIRC5 were upregulated, while AGER, TEK, CLIC5, MAMDC2, EMCN, and SEMA3G were mostly downregulated in multiple cancer types." (PMID 40535574, 2025). "This study showed AGER is underexpressed in LUAD compared with normal lung tissues; underexpression was correlated with a poorer cancer prognosis." (PMID 40563443, 2025). "Along with its pro-inflammatory role, AGER overexpression promotes migration, invasion, and epithelial–mesenchymal transition (EMT), features of cancer cells, through ERK signaling." (PMID 39409043, 2024). "AGER has been found to be downregulated in NSCLC cancer cells, and its overexpression has been shown to suppress cancer cell proliferation, invasion, and migration, while promoting apoptosis." (PMID 37217594, 2023). "RT-qPCR and Western blot results showed that the expressions of AGER, CD69, and IL7R in cancer tissues were significantly lower than those in adjacent tissues." (PMID 36358600, 2022). "To investigate the grade of cancer cells, we explored alveolar type I (AT1) and alveolar type II (AT2) cells with annotated markers, including PDPN, AGER, ABCA3, and SFTP gene families." (PMID 35874770, 2022). "Taken together, stronger staining with both anti- AGER/RAGE and -DGKK antibodies was observed in HCC cancer cells treated with high-dose ascorbate (4.0 g/kg/3 days IP)." (PMID 31754384, 2019). "Third, extracellular reduced HMGB1 induces autophagy and tumor growth through AGER/RAGE (advanced glycosylation end product-specific receptor), whereas oxidized HMGB1 induces apoptosis in cancer cells." (PMID 25126737, 2014). "In addition, autophagy-dependent ferroptosis of cancer cells release KRASG12D proteins via exosomes, which are uptaken by AGER expressed on macrophages, inducing differentiation of macrophages from a M1-like phenotype to a M2-like tumor-supportive phenotype via STAT3-dependent fatty acid oxidation." (PMID 38007476, 2023). "Besides, ferroptotic cancer cells also release HMGB1 in an autophagy-dependent manner, which binds to AGER and promotes inflammatory responses in macrophages (however, the increased inflammatory TNF cytokine production was only confirmed at the transcription level)." (PMID 38007476, 2023).
cancer (continued). "The HMGB1 released by ferroptotic cancer cells activated innate immune cells and triggered an inflammatory response that was dependent on HMGB1 binding to the cognate receptor, advanced glycosylation end product-specific receptor (AGER), and not toll-like receptor 4 (TLR4) on macrophages." (PMID 35065965, 2022).
cardiovascular disease (11 papers, 2017 to 2025). "Review of the literature suggests that the links of AGER SNPs to cardiovascular disease (CVD) may be dependent on ethnicity." (PMID 32211423, 2020).
neurodegenerative disease (10 papers, 2015 to 2025). A disorder of the central nervous system characterized by gradual and progressive loss of neural tissue and neurologic function. "RAGE (alias for AGER gene) has been reported to participate in the pathophysiological process of various diseases, including cancers, pulmonary diseases, and neurodegenerative diseases." (PMID 35358337, 2022).
adenocarcinoma (3 papers, 2013 to 2022). A common cancer characterized by the presence of malignant glandular cells. "Of the canonical changes noted, promoter (PR) DM loci with reciprocal changes in expression in adenocarcinomas included HBEGF, AGER, PTPRM, DPT, CST1, MELK; DM GB loci with concordant changes in expression included FOXM1, FERMT1, SLC7A5, and FAP genes." (PMID 26683690, 2015).
AGER also shares sentences with these, for which no sentence is quoted: infection (17 papers); Nephropathy (9); Cognitive impairment (8); acute respiratory distress syndrome (7); endothelial dysfunction (6); lupus (6); melanoma (6); ischemic stroke (5); Cerebral ischemia (4); depression (4); metabolic disorders (4); myocardial infarction (4); glioblastoma (3); lung injury (3); Myocardial fibrosis (3); ovarian carcinoma (3); preeclampsia (3); sarcopenia (3); acute kidney injury (2); acute lung injury (2); allergic asthma (2); anemia (2); anxiety disorder (2); bacterial Sepsis (2); brain injury (2); cardiac hypertrophy (2); colitis (2); coronary atherosclerosis (2); cystic fibrosis (2); dementia (2).
A further 99 diseases each share a sentence with AGER in 2 papers or fewer.